IL6 (interleukin 6)
Diseases named in the same sentence as IL6 in open-access papers (continued):
Sharing a sentence is not in itself a finding about the gene and the disease.
myocarditis (continued). "Notably, IL-6, a key pro-inflammatory cytokine, has been identified as significantly upregulated in cardiac tissue during severe manifestations of myocarditis, alongside elevated serum levels." (PMID 39202593, 2024). "Overall, myocardial macrophage and lymphocyte densities were positively associated with symptom duration and myocarditis was more prevalent with IL-6 blockade than with non-biological immunosuppression." (PMID 39026189, 2024). "For instance, in myocarditis, IL-6-triggered increases in liver complement C3 and Th17 cells may exacerbate inflammation." (PMID 38495094, 2024). "Therefore, the potential mechanism of myocardial damage in MIS-C can be the cytokine storm, induced IL-6 that leads to fulminant myocarditis development." (PMID 36674665, 2023). "Another study also revealed that Icariin could downregulate the mRNA levels of TNF-α, ICAM-1, IL-2, and IL-6, which attenuates myocardial inflammation." (PMID 36984421, 2023). "Thus, patients with myocarditis after BNT162b2 vaccination displayed a hallmark of decreased IFN (type I and type III) signaling and increased IL-6 production, which resembles the characteristics of bronchial epithelial cells." (PMID 37264110, 2023). "IL-6 KO mice with autoimmune myocarditis showed a reduction in inflammatory responses, the proliferation of autoreactive CD4+ T cells, and the expression of ICAM-1 and VCAM-1, which reduced myocarditis susceptibility." (PMID 35402550, 2022). "When myocarditis occurred, neutrophil to lymphocyte ratio, C-reactive protein, lactate dehydrogenase, interleukin (IL)-6, IL-10, creatine kinase, MB isoenzyme of creatine kinase, and brain natriuretic peptide increased from baseline, but absolute lymphocyte count decreased." (PMID 35924238, 2022). "In light of the TFR1 level has been demonstrated significantly increased in acute myocarditis patients and associated with augmented inflammation (CRP, IL-6), we hypothesized that TFRC might be a key effector gene of pro-ferroptosis in CVB3 infection." (PMID 35821227, 2022). "Our results showed increased levels of IL-6 and IL-8 in serum from myocarditis patients." (PMID 35265721, 2022). "In addition to IFN-γ and IL-17, our model had cytokine profiles similar to those of myocarditis patients, including elevated levels of IL-6 and GM-CSF." (PMID 33466825, 2021). "Interestingly, overexpression of IL-6 also accelerates myocarditis in mice, suggesting that IL-6 levels must be carefully controlled to optimize the antiviral response." (PMID 34696354, 2021). "In myocarditis, the primary sources of IL-6 are likely cardiomyocytes and cardiac fibroblasts." (PMID 33833766, 2021). "Marked activation of inflammatory cytokines including tumor necrosis factor-α (TNF-α) and interleukin (IL)-6 could be involved in the pathogenesis of myocarditis." (PMID 34926619, 2021). "Our findings of increased serum and cardiac IL-6 in the TTI-101-treated group, coupled with increased cardiac gene expression of NF-κB, uncover an IL-6/PI3K/NF-κB pro-inflammatory cascade as a potential important contributor to the intense myocarditis seen in these animals." (PMID 34504808, 2021). "Importantly, IL-6 knockout (KO) mice infected with T. cruzi were shown to have reduced myocarditis compared to wild-type mice, confirming the role of IL-6 in T. cruzi-induced inflammation." (PMID 34504808, 2021). "It has been indicated that inflammatory reactions are implicated in myocarditis and that a wide range of inflammatory factors, including TNF-α and IL-6, might be toxic to myocardial cells." (PMID 32515469, 2020). "Recently, accumulating data obtained from patients with myocarditis/endocarditis and systemic autoimmune diseases, particularly rheumatoid arthritis and other connective tissue diseases, demonstrated that circulating IL-6 levels are elevated in these patients." (PMID 33071805, 2020).
myocarditis (continued). "Similarly, digoxin blocked the lipopolysaccharide-stimulated secretion of IL-6, IL-8, and TNF-α from mononuclear cells, but promoted the expression of TNF-α and IL-6 in the heart of mice with myocarditis." (PMID 33101052, 2020). "Studies have shown that the overwhelming production of pro-inflammatory cytokines (such as TNF-α, IL-1, and IL-6) significantly aggravates myocarditis while inhibiting the expression of the inflammatory cytokines by gene knockout, significantly improving myocardial injury." (PMID 28197102, 2017). "IL-6 is a pro-inflammatory cytokine critically involved in the pathogenesis of myocarditis." (PMID 27501319, 2016). "Assuming that hepcidin expression in myocarditis is a response to IL-6, it might be possible to improve FA cardiomyopathy by blockade of IL-6 signaling." (PMID 25738292, 2015). "However, the IL-6 mRNA levels were significantly higher in the 0.1 mg/kg nicotine group than in the myocarditis group." (PMID 26507386, 2015). "IL-6 might facilitate myocardial fibrosis by regulating downstream IL-17A, promoting the progression of myocarditis into DCM." (PMID 23977238, 2013). "Both human KD patients and LCWE-treated mice developed coronary arteritis, myocarditis, valvulitis, and pericarditis, as well as elevated plasma levels of interleukin (IL)-2, IL-6, IL-10, monocyte chemoattractant protein (MCP)-1, and tumor necrosis factor (TNF)-α in acute phase." (PMID 22737215, 2012). "MSCs increased significantly the myocardial expression of HGF and decreased the expression of the proinflammatory cytokines TNFα, IL1β and IL6 as well as the severity of myocarditis and ameliorated the left ventricular dysfunction measured by conductance catheter." (PMID 22815907, 2012). "Moreover, PC could reduce IL‐6 and Caspase‐1 expression and could have promising properties to decrease LPS‐induced myocarditis outcomes." (PMID 40387469, 2025). "Scrub typhus-induced myocarditis involves immune-mediated damage triggered by the host's inflammatory response, including elevated levels of cytokines such as tumor necrosis factor-alpha, interleukin-6, and interleukin-1β, which can induce cardiomyocyte injury." (PMID 40895922, 2025). "Lack of excessive IL-2, IL-6 or IFN-γ responses in our TIM-3 deficient patient highlights the view that immunological presentations in SPTCL/HLH or primary HLH are different from the myocarditis case described here." (PMID 38485795, 2024). "Importantly, our results suggest that myocarditis might promote regeneration at least partially by stimulating HMGB1/IL-6/STAT3-dependent NGC proliferation." (PMID 39200277, 2024). "This may explain the production mechanism of IL-6, INF-β and TNFα in myocarditis patients and, in part, the chronic aspect of the disease, while IL-6 promotes platelet production by acting upon megakaryocytes and hepatocytes (increased release of thrombopoietin)." (PMID 37508529, 2023). "However, IL-6 was significantly higher in myocarditis serum compared to controls." (PMID 35265721, 2022). "For instance, considering that opioid use exacerbates the up regulation of IL-6, it may worsen the inflammation and consequent cardiovascular outcomes (e.g., myocarditis, plaque rupture) related to the cytokine storm of L-6, IL-7, and IL-22 induced by the viral invasion of SARS-CoV-2." (PMID 34803676, 2021). "Indeed, the transcription factor STAT3 by its protective cardiac function, helping maintain metabolic homeostasis, may contribute to myocarditis due to enhanced cardiac IL-6 production and thereby IL-6-induced complement component C3 production." (PMID 31844116, 2019). "In parallel, myocardial inflammation was induced via nitric oxide production, neutrophil accumulation (myeloperoxidase activity) and activation of the p38-mitogen-activated protein kinase pathway resulting in cytokine release (tumor necrosis factor-alpha, interleukin-6) in control vs. sham animals." (PMID 23663695, 2013).
myocarditis (continued). "Inflammatory and immunohistochemical markers such as CRP, IL-6, fibronectin, desmin, complement C5b-9, and S100A1 contribute to the identification of early ischemia and myocarditis, particularly when routine histology is inconclusive." (PMID 41596321, 2026). "The intersection of LC and myocarditis-related targets was visualized with a Venn diagram, revealing 51 common targets, including TNF, IL1B, IL6, and others." (PMID 41585875, 2025). "In light of these events, early reduction of IL-1β and IL-6 is imperative for managing post-vaccine cytokine storms, ACS, and myocarditis." (PMID 39452475, 2024). "IL-6 is a fundamental cytokine for myocarditis development, since EAM models IL-6−/− are resistant to myocarditis development." (PMID 39768171, 2024). "IL-6 and IL-10 were most consistently found to be elevated among patients with ICI-induced myocarditis." (PMID 36672615, 2023). "Cardiac macrophages and fibroblasts produce IL-6, which is crucial for myocarditis exacerbating into DCM, while IL-6 inhibition reduces angiotensin II-induced cardiac fibrosis." (PMID 36827455, 2023). "Previous in vitro experiments revealed that Wnt5a activates CFs and induces IL-6 and TIMP-1 synthesis, thereby promoting the occurrence of myocarditis and myocardial fibrosis." (PMID 36404310, 2022). "It has been reported that the proinflammatory cytokines IL-1β, IL-6, and TNF-α are increased in acute myocarditis." (PMID 35265721, 2022). "An extremely robust cytokine storm given by interleukin-1 (IL-1), IL-2, IL-6, IL-8, TNF-α and MCP-1 is also the main pathophysiological mechanism described for fulminant myocarditis." (PMID 34359355, 2021). "Further detection of inflammatory factors, including Tnf-α, Il-1β, Il-6, and Mcp-1, also supports the notion that geniposide attenuates HFD-induced myocardial inflammation." (PMID 30533173, 2018). "On day 7, the mRNA levels of the IL-6 and TNF-α in the myocarditis group were significantly upregulated compared with the normal group." (PMID 24225056, 2013). "On day 7, the mRNA levels of the IL-6 and TNF-α were significantly lesser in the carvedilol group compared with the myocarditis group (P < 0.05)." (PMID 24225056, 2013). "Our data demonstrate increased cardiac expression of pro-inflammatory cytokines as shown here exemplarily for TNF-α, IFN-β, IL-6 and IFN-γ in acute myocarditis in both β5i/LMP7+/+ and β5i/LMP7-/- mice." (PMID 21909276, 2011). "Theoretical benefit via IL-6 pathway inhibition exists for inflammatory myocarditis subtypes, but the absence of safety/efficacy data in EMB-proven cases contraindicates off-label use per the 2025 ESC guidelines." (PMID 41511355, 2025). "While IL-6 and TNF-α have traditionally been at the forefront of inflammatory research in HF, IL-8 has gained attention for its specific contributions to neutrophil-driven myocardial inflammation and tissue damage." (PMID 41210347, 2025). "No large-scale clinical trials specifically test IL-6 inhibitors such as tocilizumab, sarilumab, or ziltivekimab directly for the treatment of primary myocarditis." (PMID 41511355, 2025). "Our previous studies have supported a Th17 autoimmune pathogenesis where IL17A and IL-6 are elevated in myocarditis patients who do not recover normal EF." (PMID 40181955, 2025). "Interestingly, the protein expression level of HMGB1, an alarmin that activates the IL-6/STAT3 signaling pathway, was significantly higher (1.6 folds; *** p < 0.001) in endomyocardial biopsies from patients diagnosed with myocarditis compared to controls." (PMID 39200277, 2024). "There was no observed correlation between the histologic grade of myocarditis and the levels of IL-6 and TNF-α (Supplement S2)." (PMID 38785743, 2024). "Serum IL-6 (3.5ng/L) was not elevated during myocarditis episode or when the patient was asymptomatic (normal < 7ng/L)." (PMID 38485795, 2024).
myocarditis (continued). "Although specific studies on CT-1 in the context of arboviral infections are lacking, IL-6 is well documented in connection with severe dengue and cardiac issues such as myocarditis." (PMID 39772209, 2024). "However, the inflammatory M1 polarity genes (IL-1β, IL-6, TNF-α and MCP-1) were significantly increased, with increased rates of myocarditis in the heart of KO mice compared to those of WT mice." (PMID 36982385, 2023). "The first case of myocarditis was in a 63-year-old male with no significant past cardiac medical history who was noted to have elevated interleukin-6 (IL-6) and myocardial injury markers such as troponin I, who subsequently died." (PMID 37168413, 2023). "Activated monocytes release cytokines (such as IL-6 and IL-1β) into the peripheral circulation to regulate the myocardial inflammatory response and, under the influence of the chemokine MCP-1, migrate to the site of myocardial inflammation." (PMID 37512058, 2023). "The repair role of APE1/Ref-a is also suggested from findings of a murine myocarditis model in that APE1/Ref-1 is elevated at a later time point, in contrast to that of other markers, such as IL-1β, IFN-β, and IL-6 expression, which disappear with a decline in virus titer." (PMID 35052869, 2022). "The patients with myocarditis also showed high levels of IL-1 receptor antagonist (interleukin 1), IL-5, and IL-16 but no proinflammatory cytokines, for example, IL-6, tumor necrosis factor, IL-1B, IL-2 or interferon-γ." (PMID 36498573, 2022). "The 12 patients who experimented myocarditis at the admission had similar values of NT-proBNP, high sensitivity troponin T and IL-6 than the patients without myocarditis." (PMID 33663062, 2021). "Myocarditis-NCV was classified as immune-mediated when anti-heart Abs were positive, viruses in cardiac tissue were absent, myocardial TLR-4 was overexpressed and inflammatory cytokines (IL-1β, IL-6, IL-8, TNF-α) in serum samples were elevated." (PMID 33355356, 2021). "It is thereby not surprising that IL-6 concentrations are elevated in the serum and myocardium of patients with HF and myocarditis, while also being predictive of adverse outcomes." (PMID 33833766, 2021). "Bazedoxifene inhibits IL-6/STAT3 signaling in cancer cells, but its effect on the Th17 immune response induced by myocarditis remains unknown." (PMID 33643041, 2020). "IL-6 and TNF-α are both involved in the pathogenesis of myocarditis and may induce advanced cardiac dysfunction." (PMID 22761780, 2012). "Without IL-6 to regulate the early immune response after infection, the heightened early inflammatory response leads to increased chronic myocarditis severity as the disease progresses." (PMID 19587788, 2009). "The βAR signaling component in serum of myocarditis patients, however, was not IL-6 in this study but was IgG which could be blocked in its signaling activity by anti-IgG beads." (PMID 40181955, 2025). "Although IL-6, CXCL9, CXCL10 and CXCL13 levels appear to provide modest diagnostic accuracy for identifying patients with ICI-induced myocarditis, these were not fully validated in larger populations, and more data are required before clinical application is feasible." (PMID 36672615, 2023). "Most tested patients (six of seven patients) had serum increases in the inflammatory cytokine interleukin (IL)-6 and in the chemokines CXCL9, CXCL10, and CXCL13, and the mass cytometry phenotypes of immune cell populations in the blood also showed correlations with myocardial inflammation." (PMID 34686542, 2021). "The role of βAR is not well known on fibroblasts, but studies suggest it may play a role in activation of fibroblasts to secrete cytokines such as IL-6, which is one of the 2 cytokine biomarkers we have identified as a biomarker of non-recovery in myocarditis patient blood." (PMID 40181955, 2025).
myocarditis (continued). "Our study demonstrates that although IL-6 and TNF-α are commonly elevated in patients with ICI myocarditis, they did not significantly predict MACEs or 90-day mortality." (PMID 38785743, 2024). "Thus, aberrant IL-6/STAT3-mediated induction of liver acute phase response genes including C3, which occurs as a consequence of pre-existing inflammatory conditions, might represent an important factor determining the degree of myocarditis and its clinical outcome." (PMID 23460527, 2013).
uveitis (150 papers, 2008 to 2025). An inflammatory process affecting a part of or the entire uvea. "Tests involving the detection of cytokines like interleukin 6, interleukin 10, and PCR detection of pathogenic nucleic acids hold significant clinical relevance in uveitis diagnosis." (PMID 40851860, 2025). "Research work indicates that uveitis is strongly associated with inflammatory and immune cytokines, including tumor necrosis factor, interleukin 1 (IL-1), IL-2, IL-6, IL-8, and interferon gamma (IFN-γ)." (PMID 40687721, 2025). "Key cytokines associated in uveitis include interleukins (IL), specifically IL-6 and IL-17, tumor necrosis factor alpha (TNF-α), and interferon gamma (IFN-γ), each exhibiting distinct effects on the pathogenesis of uveitis." (PMID 39075390, 2024). "JAK inhibitors block multiple pro-inflammatory cytokines implicated in human uveitis such as IL-6 and IFNγ, resulting in disruption of Th1 differentiation." (PMID 35998207, 2022). "Studies have shown that IL-6 plays a critical role in animal models of uveitis and that either IL-6 deficiency or anti-IL-6 treatment results in diminished uveitis and that elevated IL-6 is also detected in human uveitis." (PMID 36313265, 2022). "There was a positive correlation between IL-6 and IL-8 levels and the number of neutrophils present in patients with uveitis aqueous humor associated with Fuchs' heterochromic cyclitis." (PMID 35178133, 2022). "The proinflammatory factors TNF-α, IL-1β and IL-6 are also associated with the development of uveitis." (PMID 35625654, 2022). "Various studies in the literature show association of inflammatory disorders like uveitis, retinal vascular occlusions, and diabetic macular edema with increased levels of IL-6." (PMID 31523783, 2019). "This is a novel adaptive design study of subcutaneous IL-6 inhibition in anti-TNF refractory JIA associated uveitis which will be able to determine if further research should be conducted." (PMID 30886955, 2018). "IL-6 was proved to be associated to many ocular pathologies related to inflammations, such as uveitis, glaucoma, ocular neovascularization and autoimmune disease." (PMID 29440661, 2018). "The infection of guinea pigs with the L. interrogans serovar Icterohemorrhagiae increased the levels of IL-6 and TNFα mRNA in the lungs, and uveitis of leptospiral origin was associated with an increased production of the cytokines IL-6 and IL-8." (PMID 23132959, 2012). "TNFα and IL-6, characteristic proinflammatory cytokines, are thoroughly implicated in BD aggravation, as they are released by monocytes and T lymphocytes in patients with BD uveitis, and participate in the formation of BD lesions, such as ocular lesions." (PMID 39798064, 2025). "Additionally, patients with HLA-B27-associated uveitis and Behçet’s exhibit higher levels of IL-6 compared to patients with VKH disease, sarcoidosis, and idiopathic granulomatous uveitis." (PMID 40433375, 2025). "The activation of Th17 cells with Th17-related proinflammatory cytokine induction (IFN-γ, TNF-α, IL-1β, IL-6, IL-23) could result in spondyloarthritis with associated uveitis." (PMID 35087531, 2021). "Furthermore, the uveitis seen in leptospirosis is associated with a rise in IL-6, IL-8, TNF-α, and IL-10 production." (PMID 23132959, 2012). "Besides, clinical uveitis can be caused not only by IL-1 but also by other cytokines such as IL-6, IL-10, and tissue necrosis factor, etc." (PMID 19693263, 2009). "This trial is a novel adaptive design study of subcutaneous IL-6 inhibition in anti-TNF refractory JIA associated uveitis which will be able to determine if further research into the use of this intervention for the treatment of anti-TNF refractory JIA-associated uveitis should be conducted." (PMID 30886955, 2018).